CDC42 (cell division cycle 42)
Description:
Plasma membrane-associated small GTPase which cycles between an active GTP-bound and an inactive GDP-bound state. In active state binds to a variety of effector proteins to regulate cellular responses. Involved in epithelial cell polarization processes. Regulates the bipolar attachment of spindle microtubules to kinetochores before chromosome congression in metaphase. Regulates cell migration. In neurons, plays a role in the extension and maintenance of the formation of filopodia, thin and actin-rich surface projections. Required for DOCK10-mediated spine formation in Purkinje cells and hippocampal neurons. In podocytes, facilitates filopodia and podosomes formation upon DOCK11-activation. Upon activation by CaMKII, modulates dendritic spine structural plasticity by relaying CaMKII transient activation to synapse-specific, long-term signaling (By similarity). Also plays a role in phagocytosis through organization of the F-actin cytoskeleton associated with forming phagocytic cups. Upon activation by PLEKHG4B, involved in actin cytoskeletal remodeling during epithelial cell-cell junction formation. Negatively regulates polymerization of SEPTIN12, as a result may be involved in spermatogenesis.
Synonyms: G25K; CDC42Hs; TKS
Tractability: Small molecule: a structure with a bound ligand is known; a high-quality ligand is known; it has a high-quality binding pocket; it belongs to a druggable protein family. Antibody: UniProt places it where antibodies can reach, with high confidence; its Gene Ontology location is reachable by antibodies, with high confidence. PROTAC: ubiquitination databases record sites on it; its protein half-life has been measured; a small molecule that binds it is known.
Target class: Enzyme; Hydrolase
Chemical probes: ML-097, ML-098, ML-099, ML141
Gene: Protein-coding gene on chromosome 1 (22,052,627 to 22,101,360, forward strand). Ensembl gene ENSG00000070831.
Subcellular location: Cell membrane; Cytoplasm, cytoskeleton, microtubule organizing center, centrosome; Cytoplasm, cytoskeleton, spindle; Midbody; Cell projection, dendrite; Cytoplasmic vesicle, secretory vesicle, acrosome
Subcellular location (Human Protein Atlas): Microtubules; Cytokinetic bridge
Pathways (Reactome):
Signal Transduction: CDC42 GTPase cycle; EGFR downregulation; G beta:gamma signalling through CDC42; MAPK6/MAPK4 signaling; RAC1 GTPase cycle; RAC2 GTPase cycle; RAC3 GTPase cycle; RHO GTPases Activate Formins; RHO GTPases Activate WASPs and WAVEs; RHO GTPases activate IQGAPs; RHO GTPases activate KTN1; RHO GTPases activate PAKs; RHOG GTPase cycle; RHOJ GTPase cycle; RHOQ GTPase cycle; RHOU GTPase cycle; RHOV GTPase cycle; VEGFA-VEGFR2 Pathway
Developmental Biology: DCC mediated attractive signaling; EPHB-mediated forward signaling; Inactivation of CDC42 and RAC1; Myogenesis
Immune System: CD28 dependent Vav1 pathway; Gene and protein expression by JAK-STAT signaling after Interleukin-12 stimulation; Regulation of actin dynamics for phagocytic cup formation
Cell-Cell communication: Activation of STAT3 by cadherin engagement; SRC activates STAT3 in a quantitative manner, through Cadherin-11 (CDH11), RAC1 and gp130 (IL6ST)
Hemostasis: Factors involved in megakaryocyte development and platelet production; GPVI-mediated activation cascade
Disease: FCGR3A-mediated phagocytosis
Gene Ontology:
Molecular function: apolipoprotein A-I receptor binding; GBD domain binding; GTP binding; GTPase activity; identical protein binding; protein binding; protein kinase binding; thioesterase binding; ubiquitin protein ligase activity; G protein activity; GTP-dependent protein binding
Biological process: actin cytoskeleton organization; actin filament organization; cell junction assembly; establishment of epithelial cell apical/basal polarity; host-mediated perturbation of viral process; integrin-mediated signaling pathway; negative regulation of protein-containing complex assembly; neuropilin signaling pathway; phagocytosis, engulfment; positive regulation of cell growth; positive regulation of cell migration; positive regulation of cytokinesis; positive regulation of filopodium assembly; positive regulation of lamellipodium assembly; positive regulation of pseudopodium assembly; positive regulation of stress fiber assembly; positive regulation of substrate adhesion-dependent cell spreading; regulation of actin cytoskeleton organization; regulation of attachment of spindle microtubules to kinetochore; regulation of filopodium assembly; regulation of lamellipodium assembly; regulation of stress fiber assembly; substantia nigra development; dendritic spine morphogenesis; endocytosis; and 17 more
Cellular component: centrosome; cytoplasm; cytoplasmic ribonucleoprotein granule; extracellular exosome; filopodium; focal adhesion; Golgi transport complex; membrane; microtubule cytoskeleton; midbody; mitotic spindle; neuron projection; neuronal cell body; plasma membrane; protein-containing complex; spindle midzone; cytosol; endoplasmic reticulum membrane; Golgi membrane; acrosomal vesicle; apical part of cell; cell leading edge; cell periphery; cell-cell junction; dendrite; and 6 more
Genetic constraint (gnomAD): Loss-of-function variants: 1 observed, 7.76 expected, observed/expected ratio (o/e) 0.13, 90% interval 0.045 to 0.61. That is too few expected variants to judge how well the gene tolerates losing a copy. Missense variants: 30 observed, 115.48 expected, observed/expected ratio (o/e) 0.26, 90% interval 0.19 to 0.35. Synonymous variants: 37 observed, 40.37 expected, observed/expected ratio (o/e) 0.92, 90% interval 0.7 to 1.21.
Gene-disease validity (ClinGen):
ClinGen rates the evidence that CDC42 causes each of these diseases.
macrothrombocytopenia-lymphedema-developmental delay-facial dysmorphism-camptodactyly syndrome (autosomal dominant): Definitive.
Homologues: Orthologues: chimpanzee CDC42 (100% identical), dog CDC42 (100% identical), guinea pig CDC42 (100% identical), macaque CDC42 (100% identical), mouse Cdc42 (100% identical), zebrafish cdc42 (99% identical), tropical clawed frog cdc42 (98% identical), rat Cdc42 (95% identical), Drosophila melanogaster Cdc42 (93% identical), zebrafish cdc42l (91% identical), Caenorhabditis elegans cdc-42 (86% identical), pig CDC42 (86% identical). Paralogues in human: RAC1 (71% identical), RAC3 (70% identical), RAC2 (69% identical), RHOQ (69% identical), RHOJ (63% identical), RHOG (61% identical), RHOU (58% identical), RHOV (53% identical), RHOC (51% identical), RHOA (50% identical), RHOB (50% identical), RHOBTB2 (47% identical), and 10 more.
Diseases named in the same sentence as CDC42 in open-access papers:
CDC42 is named in the same sentence as 361 diseases in open-access papers, as found by Europe PMC text mining. Sharing a sentence is not in itself a finding about the gene and the disease. The quoted sentences say what the papers report.
breast carcinoma (173 papers, 2005 to 2026). "Nevertheless, Cdc42 (together with Rac1) plays a role at least in the DF variant-promoted activation of MLKL in the T-47D breast cancer cells." (PMID 39062543, 2024). "There was weaker evidence of colocalization of the CDC42 expression (using summary data from the eQTLGen platform) and breast cancer risk signals." (PMID 35087170, 2022). "The association between drug resistance and overexpression of CDC42 was implicated in breast cancer cells." (PMID 36430822, 2022). "There was some suggestive evidence that increased expression of cell division cycle 42 (CDC42) was inversely associated with overall and ER+ breast cancer risk." (PMID 35087170, 2022). "Using eQTLs from breast cancer tissue and normal blood there was some evidence that CDC42 was negatively associated with overall and ER + breast cancer risk." (PMID 35087170, 2022). "Promoter in gastric cancer in association with α3 integrins.Promoter in breast cancer in association with integrins promoting a signaling pathway (HGF/c-MET).Promoter in liver cancer by increasing Rac/Cdc42 activity." (PMID 34830819, 2021). "As disruption of epithelial architecture is a hallmark of breast cancer, Bray and colleagues developed a TetO-Cdc42-overexpressing mouse model to study the effects of Cdc42 on epithelial structure." (PMID 32992837, 2020). "Specifically in breast cancer, Rac/Cdc42/PAK signaling is implicated with therapy resistance of HER2-type, triple negative, and ER(+) cancers." (PMID 32322580, 2020). "This review focuses on some important aspects of breast cancer processes and discusses the association between Rho GTPase, Cdc42 and breast cancer." (PMID 30754684, 2019). "Hyperactivation of the cancer stem cell (CSC) pool in breast cancer patients with hyperglycemia is associated with miR-424 regulation of Cdc42." (PMID 30754684, 2019). "Cdc42 expression is up-regulated in breast cancer, however loss of Cdc42 enhances liver cancer development, suggesting that the multiple roles of Cdc42 affect cancer progression in a tissue-specific manner." (PMID 24279335, 2013). "Aberrant Rac and Cdc42 activities have been recently associated with invasive and malignant behavior in a variety of cell types, including hepatocarcinoma, breast carcinoma, and melanoma." (PMID 16280046, 2005). "Although this was not investigated in this study, our previous work has shown that a loss of Bcl3 can regulate CDC42 transcription in breast cancer cell lines, including MCF-7 cells, which could also contribute to ROS production and senescence." (PMID 38255248, 2024). "To explore whether oncogenic alterations in Rho/Rac1/CDC42 signaling are further enriched in metastatic vs primary breast cancer, we compared the rate of missense mutations and copy number alterations (CNA) in 42 genes associated with these pathways." (PMID 37463901, 2023). "We found robust evidence that RHOD expression may be causally and positively related to breast cancer risk, and that CDC42 may potentially be causally and negatively related to breast cancer risk." (PMID 35087170, 2022). "Consequently, loss of RhoGDIα caused increased Rho, Rac-1 and Cdc42 activities in breast cancer cells." (PMID 26554417, 2015). "The proposal that WNT‐5A increases breast cancer cell migration is compatible with its capacity to increase Cdc42 activity in fibroblasts and non‐tumorigenic breast epithelial cells, since Cdc42 activity is commonly associated with increased cell migration." (PMID 23727359, 2013). "Primarily, Rho, Cdc42, and Rac proteins are associated with tumorigenesis and cardiovascular disease, including lymphomas, Kaposi’s sarcoma, prostate cancer, gastric cell carcinoma, breast cancer, non-small cell lung cancer, squamous cell carcinoma, and glioblastoma." (PMID 37221195, 2023).
breast carcinoma (continued). "Given that the activity of RHOD and CDC42 proteins is regulated by a variety of other proteins, it will be interesting to determine whether any of the genes encoding these regulators are also associated with breast cancer risk." (PMID 35087170, 2022). "miRNAs such as miR-136-5p and miR-138-5p, which target CDC42 and other GTPase regulators, have been shown to inhibit invasion and metastasis in breast cancer." (PMID 41516402, 2026). "Previous reports demonstrated that NSL-YHJ-2-27 depletes the cellular levels of some G-proteins, such as RAC1 and CDC42, in both lung and breast cancer cell lines." (PMID 40736275, 2025). "PLC-γ1 regulates Rac1 and CDC42 GTPases through I P3-induced calcium release, playing a critical role in breast cancer lung metastasis; inhibiting PLC-γ1 significantly reduces its metastatic potential." (PMID 40519297, 2025). "Shifting of the apical CDC42 to the basolateral side with phosphorylated aPKCζ cytosolic accumulation and nuclear accumulation CDC42 is found to drive aggressive proliferation of ER positive low-grade breast cancer." (PMID 40057606, 2025). "It has been reported that p120 increases the migration and invasion ability of the epidermal growth factor receptor 2-induced breast cancer cells through inducing Rac1 and Cdc42 activity." (PMID 39498333, 2024). "CDC42 and c-CBL are the critical components involved in the regulation of EGFR protein levels, and restoring proper EGFR degradation by disrupting the regulation of c-CBL by CDC42 can effectively reduce the proliferation and migration of breast cancer cells." (PMID 39130630, 2024). "Upon EGF stimulation, RhoGDI1 phosphorylated at Ser174 binds to 14-3-3, promoting the dissociation of RhoA, Rac1 and Cdc42, which leads to their activation and results in cancer cell invasion and breast cancer metastasis." (PMID 39768163, 2024). "Protein phosphatase 1B (PPM1B) dephosphorylates RhoGDI1 at Ser174, reduces RhoGDI1 interaction with 14-3-3, thereby inhibiting signaling of RhoA, Rac1, and Cdc42 in breast cancer cell migration." (PMID 39768163, 2024). "MDA-MB-231 breast cancer cells were transfected with Rac1, Cdc42, or RhoA biosensors and treated with P18 at a concentration of 25 μg/mL for 3 h." (PMID 38927935, 2024). "Altogether, our data suggest that the brain endothelium and EGF contribute to extravasation by promoting DOCK4/RAC1- and DOCK9/CDC42-mediated elongation and intercalation of breast cancer cells." (PMID 38762624, 2024). "This approach will help elucidate the potential reciprocal regulation of RAC1, CDC42 and their activating GEFs in brain homing breast cancer cells." (PMID 38762624, 2024). "Further exploration through individual cancer stages revealed that breast cancer patients exhibited heightened expressions of both CDC42 and ACTR2 across all AJCC (American Joint Committee on Cancer) stages, distinguishing them from normal patients." (PMID 38612766, 2024). "In another study, it was discovered that the REDOX/Fyn/c-CBL (RFC) pathway, which typically translates the slight increase in oxidation into the accelerated degradation of c-CBL target proteins, was inhibited by Cdc42 in basal-like breast cancer (BLBC) cells." (PMID 39130630, 2024). "CDC42 is frequently overexpressed in many cases of breast cancer, and evidence suggests that activated CDC42 enhances the accumulation of ErbB1 within cells by modulating the function of c-CBL." (PMID 39130630, 2024). "The improved EHop-016 derivative MBQ-167 demonstrated 10X higher efficacy at 100 nM IC50 for inhibition of Rac1 activation and 78 nM for Cdc42 activation in breast cancer cells." (PMID 37397366, 2023). "We previously found that TNFAIP2 was regulated by KLF5 and interacted with the small GTPases RAC1 and CDC42, thereby regulating the actin cytoskeleton and cell morphology in breast cancer cells." (PMID 37787041, 2023).
breast carcinoma (continued). "The upregulation of the expression of CDC42 is closely related to the development and metastasis of gastric cancer, breast cancer, and lung cancer." (PMID 37476838, 2023). "Ezrin binds to the GEF of Cdc42 to activate the downstream pathway of Cdc42 and promote the directed migration of breast cancer cells." (PMID 37328063, 2023). "Other researchers have found that inhibition of Cdc42 was responsible for the suppression of invasion ability in lung cancer, while the reduced RhoA had an anti-metastatic function on breast cancer." (PMID 36969843, 2023). "Kaplan–Meier OS analysis of breast cancer patients revealed that low expression of FBXW7, SRGAP2, MTMR3 as well as CDC42, the partner of CDC42BPA, is associated with poor prognosis." (PMID 37463901, 2023). "This parallel assessment allowed us to achieve close quantitative agreement of the modeled and observed dynamics of Cdc42 and Rac1 activity during cell ruffling in both breast cancer cells (MDA-MB-231) and MEF cell lines." (PMID 37371108, 2023). "CD44 3'-UTR overexpression inhibits tumor proliferation, angiogenesis, and docetaxel resistance in breast cancer by serving as a competitor to the CDC42 3'-UTR for miR-216a, miR-330, and miR-608 binding." (PMID 37771777, 2023). "EHop-016 inhibits Cdc42 activation and the viability of breast cancer cell lines at much higher concentrations (~10 μM)." (PMID 37397366, 2023). "For instance, a study found that CDC42 expression correlates positively with Ki-67 expression in breast cancer." (PMID 35399723, 2022). "By contrast, Malat1 oncogene function in breast cancer resulted in upregulation of Cdc42 by targeting and binding miR-1, which is capable of recognizing the Cdc42 3′UTR and triggering its mRNA degradation." (PMID 35447891, 2022). "GBP-2 inhibits breast cancer cell migration by inhibiting the activation of Rac1, while promoting the activation of CDC42 and RhoA." (PMID 35681772, 2022). "We previously reported on the efficacy of MBQ-167, which blocks both Rac1 and Cdc42 in breast cancer cells and mouse models of metastasis." (PMID 36861094, 2022). "For multiple SNP sensitivity analyses, the results for the effect of CDC42 on overall and ER+ breast cancer were consistent across the various sensitivity analyses." (PMID 35087170, 2022). "CuB mediates the reorganization of cytoskeletal proteins in breast cancer cells via the Rac1/Cdc42/RhoA signaling pathway, which sheds new light on the suppression of breast cancer metastasis by CuB." (PMID 36362132, 2022). "The power was > 99% for CDC42 in overall, ER+ and ER− breast cancer using eQTL obtained from blood and ≥ 27.19 using eQTL obtained from breast cancer." (PMID 35087170, 2022). "MBQ167 shows improved efficacy in metastatic breast cancer cells by inhibiting Rac activity and Cdc42 activity." (PMID 35154449, 2022). "Cell migration is largely mediated through Rho GTPase activity which is regulated by Cdc42 in a Bcl-3-dependent manner in breast cancer cell lines." (PMID 35681213, 2022). "Differences in tissue-specific CDC42 expression biasing the result are unlikely as the effects of SNPs for CDC42 were derived from both breast cancer tissue and from blood and were in concordance." (PMID 35087170, 2022). "CDC42 knockdown was also able to induce ERK5 activity in breast cancer cells, and CDC42 activation suppressed ERK5 phosphorylation in those cells." (PMID 34299213, 2021). "DLC3 (STARD8) has been identified as a Cdc42 regulator whose levels are reduced, at the mRNA level at least, in kidney, lung, ovarian, uterine and breast cancer." (PMID 34196668, 2021). "Our results identify a functional link between CD99, CDC42 and cytoskeletal dynamics in cancer cells and demonstrate that breast cancer CD99 negatively regulates CDC42 activity and TEM." (PMID 34374417, 2021). "In this study, we demonstrated a role for TC10 GTPase, a close paralog of Cdc42, at tumor invadopodia during breast cancer invasion and metastasis." (PMID 34531530, 2021).